SPMAP1 (sperm microtubule associated protein 1)
Synonyms: C17orf98; LOC388381
Tractability: No criterion of Open Targets' tractability assessment is met for any kind of drug.
Gene: Protein-coding gene on chromosome 17 (38,835,086 to 38,841,438, reverse strand). Ensembl gene ENSG00000275489.
Genetic constraint (gnomAD): Loss-of-function variants: 15 observed, 14.53 expected, observed/expected ratio (o/e) 1.03, 90% interval 0.69 to 1.58. The upper end of that interval is the gene's LOEUF score, 1.58, which puts it in group 6 of 6, group 1 being the genes least tolerant of losing a copy. Missense variants: 194 observed, 209.6 expected, observed/expected ratio (o/e) 0.93, 90% interval 0.82 to 1.04. Synonymous variants: 93 observed, 87.21 expected, observed/expected ratio (o/e) 1.07, 90% interval 0.9 to 1.27.
Homologues: Orthologues: chimpanzee SPMAP1 (100% identical), macaque SPMAP1 (97% identical), rabbit SPMAP1 (87% identical), dog SPMAP1 (84% identical), pig SPMAP1 (84% identical), rat Spmap1 (78% identical), guinea pig SPMAP1 (77% identical), mouse Spmap1 (77% identical), tropical clawed frog spmap1 (49% identical).